FBLN2 (fibulin 2)
Diseases named in the same sentence as FBLN2 in open-access papers (continued):
Sharing a sentence is not in itself a finding about the gene and the disease.
tumor (continued). "Therefore, although the absence of fibulin-2 and ADAMTS-12 is not essential for life, they play an important role in the complexity of processes such as tumor progression and inflammation." (PMID 38396702, 2024). "This was further supported by the lack of FBLN2 expression in the stromal regions of tumours where the metastatic stromal markers TN-C, POSTN, and GAGs26,47,48 were all expressed, as well as FBLN2′s presence around normal ducts where these metastatic markers were absent." (PMID 30237579, 2018).
cancer (36 papers, 2008 to 2025). A tumor composed of atypical neoplastic, often pleomorphic cells that invade other tissues. "In general, fibulin-2 participates in cellular processes such as adhesion, migration and proliferation and has also been implicated in a dual role in cancer progression." (PMID 38396702, 2024). "Since FBLN2 expression changes significantly in many cancer types, we further examined the association of the FBLN2 splicing pattern with its expression levels." (PMID 25908786, 2015). "Thus, fibulin-2 can be associated with cancer progression with a role that clearly depends on the interactions with other components of the ECM." (PMID 38396702, 2024). "FBLN2 is also up-regulated during the tissue remodeling process, and its overexpression has been associated with different chronic diseases such as fibrosis and cancer." (PMID 34440261, 2021). "In contrast, in high grade cancers FBLN2 RNA expression was associated with poor prognosis." (PMID 34565423, 2021). "We have previously reported that FBLN2 expression in DCIS (relatively early stage of cancer progression) can play a protective role against BM disruption, and therefore, high expression is advantageous." (PMID 39110274, 2024). "While seen more prominently in metaplasia-derived fibroblasts, some of the fibroblasts from cancer-bearing mucosa also showed intracellular and extracellular FBLN2 positivity." (PMID 37196797, 2023). "Cancer cell 2 expressed high levels of mesenchymal/basal-like subtype genes including Lgals1, Fbln2, Timp1, and Areg." (PMID 37998349, 2023). "Dysregulation of MAPK and AKT pathways by FBLN2 or its family members has been reported in various types of cancer." (PMID 34769264, 2021). "The effect of fibulin-3 depends on both the cell types and stage of development of cancer, like that of fibulin-2." (PMID 34063320, 2021). "The genes assayed were neuroendocrine-associated genes (INSM1, ASCL1, NRCAM, and SNAP25), one gene centered in the gene regulatory network (NUF2), and five possibly cancer-associated genes (PTP4A3, RFC4, REST, APEH, and FBLN2)." (PMID 34395507, 2021). "Univariate and multivariate analyses were performed to assess the prognostic impacts of FBLN2 staining on cancer metastasis and patient death in UC." (PMID 33194662, 2020). "The complexity of the functions of fibulin-2 is also evident in pathological conditions such as cancer." (PMID 31508361, 2019). "Fibulin-2 plays a complex role in cancer development depending upon the cell types, cancer stages, and the degree of malignancy." (PMID 30227601, 2018). "This gave a total of 244 isoform switches, with 59 of them appearing in more than one cancer type, and the most common across cancers being FBLN2." (PMID 25578962, 2015). "A statistically significant correlation was observed for AP2B1, TCF20 and FBLN2 in one or two of the cancer types examined." (PMID 25908786, 2015). "Another interesting case is Fibulin-2 (FBLN2), an extracellular matrix glycoprotein which is frequently methylated and downregulated in many cancer types." (PMID 25908786, 2015). "FBLN2 expression and clinical features in grastric cancer patient samples." (PMID 38332530, 2024). "In contrast, in other different types of cancer, a promoter role has been defined for fibulin-2." (PMID 38396702, 2024). "Therefore, the dual role of fibulin-2 in cancer is clearly dependent on the cell origin (specie) and cell type and on the interaction with other ECM components." (PMID 38396702, 2024). "Indeed, when we tested EPB41L2 and FBLN2, which are reported cancer-type-specific spliced genes, we found decreased exon skipping of EPB41L2 in breast PDX, whereas the FBLN2 gene showed increased exon skipping in colon PDX." (PMID 38069324, 2023). "Considering the extensive crosstalk between Ras-MEK-ERK1/2 mitogen-activated protein kinase (MAPK) signaling cascade and cancer cell growth, we further investigated whether this pathway was responsible for FBLN2-mediated cell growth and proliferation in HCC." (PMID 37162505, 2023).
cancer (continued). "Fibulin-2 is known to contribute to the development and progression of various cancer types." (PMID 37162505, 2023). "Interestingly, FBLN2, which presents a switch in various cancers, has been observed frequently methylated in breast and other epithelial tumors." (PMID 25578962, 2015). "Notably, two cassette exons that were altered significantly in more than four cancer types were also found among these consistently altered cassette exons; exon 9 of the gene FBLN2, and the EDB exon of the gene FN1." (PMID 25908786, 2015). "Interestingly, many of the DMGs identified had multiple roles and several were potential cancer biomarkers or were previously shown to be implicated in various types of cancers, including ABLIM1, ADAM12, ARHGEF4, FBLN2, ITGA6, LRPAP1, Ly9, NT5E, PITPNC1, PLCG1, OBSCN, RHOH, SPTBN1, SPOCK2 and SPRY1." (PMID 41159936, 2025). "Taking into account the interaction between fibulin-2 and ADAMTS-12, we generated fibulin-2/ADAMTS-12-double-deficient mice and demonstrated that they represent a new and valuable in vivo model for the functional analysis of the interaction of these two proteins in inflammation and cancer processes." (PMID 38396702, 2024). "Furthermore, cancer-derived fibroblasts showed a 2-fold higher number of PDGFRα+ fibroblasts compared with metaplasia-derived fibroblasts, and intra- or extracellular FBLN2 positivity was slightly up-regulated in metaplasia-derived fibroblasts compared with cancer-derived fibroblasts." (PMID 37196797, 2023). "Consequently, identification of processes that could lead to an altered Fibulin-2 could have a major impact not only in the maintenance of tissue architecture and morphogenesis but also in pathological situations including cancer." (PMID 28099917, 2017). "Hence, it may be proposed that although a significant change in splicing was observed for BRCA, COAD and THCA, the reduced gene expression of FBLN2 probably has a greater effect on the cancer phenotype in these cancers." (PMID 25908786, 2015). "Recent study indicates that FBLN2 may play a role during progression in a variety of cancers." (PMID 24949431, 2014). "Thus, fibulin-2 plays a more complex role in cancer than had been previously appreciated." (PMID 23785517, 2013). "Among all overlapping cancer genes regulated by these two eccMIR clusters, the downregulated expression of PIM1, KLF4, and FBLN2 was confirmed via RT-qPCR." (PMID 39920810, 2025). "Concerning CAV1, EFEMP1, FBLN2, TGFBI, or VDAC1, their actions are highly context-dependent and can vary across different cancer types and stages." (PMID 39201614, 2024). "Although not statistically significant, there was a trend toward downregulation of FBLN2 and FBLN7 in cancer tissue relative to benign." (PMID 29581841, 2018). "Taken together, it is likely that splicing changes in FN1, FBLN2, AP2B1 and TCF20 are also drivers of cancer initiation and progression, which still needs to be determined functionally." (PMID 25908786, 2015). "Some of the common cancer-regulated alternative splicing events we identified in genes such as FN1, FBLN2, AP2B1 and TCF20 are most likely oncogenic drivers." (PMID 25908786, 2015). "In the current study, we observed a negative correlation between ITGBL1 protein expression and FBLN2 protein expression in AR‐GC cell lines and GC cancer tissues." (PMID 38332530, 2024). "To verify that the absence of FBLN2 in invasive cancerous areas was not a technical artefact, we stained 10 cancer tissue sections for other known markers of invasive and metastatic spread." (PMID 30237579, 2018). "Surprisingly, most of these switches are independent of somatic mutations, except for the tumor suppressor FBLN2 and the oncogene MYH11, suggesting that recurrent isoform switching in cancer is mostly independent of somatic mutations." (PMID 25578962, 2015). "However, it is not surprising that FBLN2 exerts different functions in human and murine cancer cells." (PMID 34769264, 2021).
cancer (continued). "We selected FBLN2 for further study, as the role of FBLN2 in cancer development is not straightforward; it may inhibit or promote tumorigenesis." (PMID 33194662, 2020). "In addition, proteins that have been related to other cancers but not to BC yet, were also identified, such as fibulin-2 (FBLN2), tissue alpha-L-fucosidase (FUCA1), staphylococcal nuclease domain-containing protein 1 (SND1), and EIF3D." (PMID 29050215, 2017). "However, the role of fibulin-2 in cancer development is not straightforward; it may inhibit or promote tumorigenesis." (PMID 30227601, 2018).
infection (3 papers, 2012 to 2023). The state of being infected such as from the introduction of a foreign agent such as serum, vaccine, antigenic substance or organism. "Other proteins with increasing abundance over the course of infection common in both species at d84 vs. d0 (foxes) or d75 vs. d-7 (dogs) were, among others, fibulin 2, interleukin enhancer-binding factor 2, prosaposin, and phosphoglycerate mutase." (PMID 34832667, 2021). "FBLN2 or NPR3 deficiency did not influence MSCs proliferation within 7 days post-infection (Data not shown)." (PMID 37543430, 2023). "Furthermore, LAMA1 (Laminin, alpha 1) interacts with Fibulin-2 (FBLN2), an ECM protein that binds various extracellular ligands and calcium and appears to be involved in the infection process." (PMID 23133440, 2012).
cardiac disease (2 papers, 2014 to 2025). "However, there is information in the literatureshowing that Fibulin 2 exhibits abnormal tissue expression and increased serumlevels in some heart diseases associated with fibrosis." (PMID 40026492, 2025). "Up regulation of fibulin-1 is associated with cardiac disease, while up regulation of fibulin-2 and fibulin-3, although not implicated in cardiac disease, is associated with a variety of other fibrotic disorders." (PMID 25117565, 2014).
cardiovascular disease (2 papers, 2020 to 2023). "Other studies reported that FBLN2 is likely associated with cardiovascular disease." (PMID 37543430, 2023).
lung (1 paper, 2021). "In this study, with the goal of understanding how FBLN2 functions in human lung NSCLC cells, we began the characterization of FBLN2 in human NSCLC." (PMID 34769264, 2021).
FBLN2 also shares sentences with these, for which no sentence is quoted: adenocarcinoma (2 papers); glioma (2); non-small cell lung carcinoma (2); ovarian carcinoma (2); prostate carcinoma (2); B-cell acute lymphoblastic leukemia (1); cardiomyopathy (1); chronic hepatitis (1); clear cell carcinoma (1); colon cancer (1); connective tissue disorder (1); endometrial cancer (1); endometrioid carcinoma (1); essential hypertension (1); head and neck squamous cell carcinoma (1); hypothyroidism (1); idiopathic pulmonary fibrosis (1); Inguinal hernia (1); intracranial aneurysm (1); leishmaniasis (1); leukaemia (1); liver cancer (1); Marfan syndrome (1); metabolic disease (1); multiple sclerosis (1); myxoid liposarcoma (1); oral cancer (1); ovarian tumors (1); pancreatic adenocarcinoma (1); Primary immunodeficiency (1).
A further 11 diseases each share a sentence with FBLN2 in 1 paper.